CD4 (CD4 molecule)
Diseases named in the same sentence as CD4 in open-access papers (continued):
Sharing a sentence is not in itself a finding about the gene and the disease.
tumor (continued). "Thus, shedding a new light on the role of cDC1s in tumor immunity and providing evidence that cDC1-targeted Abs may enhance ADA induction due to their dual role in stimulating both CD8+ and CD4+ T cells." (PMID 37942313, 2023). "Thus, more CD4, DC3 and M1 macrophages within tumor tissue correlate with better survival." (PMID 37938368, 2023). "FFPE samples were immunostained for CD4+, CD8+, and CD45+ tumor-infiltrating immune cells, where 9, 15, 17, and 16; 7, 24, 14, and 12; and 3, 10, 10, and 34 samples were stained negatively, weakly, moderately, and strongly for CD4+, CD8+, and CD45+ tumor-infiltrating immune cells, respectively." (PMID 37761986, 2023). "Additionally, ML-NK cells retained >80% of their cytotoxic capacity against tumor cells even in the complete absence of CD4+ T cells." (PMID 37865647, 2023). "Although we did not perform the antibody-mediated depletion of CD8+ T cells and macrophages, the depletion of CD8+ T cells completely abrogated the anti-PD-1-induced tumor inhibition whereas the depletion of CD4+ T cells, B cells, and NK cells does not in MC38 tumor-bearing C57BL/6 mice." (PMID 36765611, 2023). "Starting from this observation, we hypothesized that modulation of the β3-AR signaling on tumor-infiltrating T cells, in particular on CD4+ and CD8+, could be responsible of an altered IFN-γ secretion, which in turn affected the PD-L1 expression on tumor cells." (PMID 36854895, 2023). "The vaccine successfully triggered and sustained CD4+ T cell help-enhanced immune responses in the intestinal tract, and then in systemic circulation and the spleen, thus allowing WT1-specific T cells to reach the tumor where they exerted obvious antitumor activity." (PMID 36803483, 2023). "The reason may be that MHC class II molecules are not constitutively expressed in most tumor cells, and therefore it is necessary for DCs to present tumor neoantigens and activate tumor-specific CD4+ T cells." (PMID 36776837, 2023). "LAIR-1 was multiplexed with lymphocyte markers (CD45RA, CD4, CD8, CD20, CD56), myeloid monocyte markers (CD14, CD68, CD163 for macrophages and CD66b for neutrophils), fibroblast marker (SMA), hematopoietic progenitor cells (HPC, CD34) and tumor marker (pan CK)." (PMID 36960400, 2023). "However, it does not allow to distinguish different immune cell types (e.g., monocytes, neutrophils, CD4+ T, CD8+ T, and B cells) or detect minor subpopulations (e.g., monocyte subsets) in cancer that can play an important role in tumor progression and prognosis." (PMID 36996049, 2023). "Given the synergistic potency of combining PD-1 blockade with NeoAg peptide vaccination and the ability of the Mut_48 peptide to induce both CD4+ and CD8+ T cell responses against the SCC VII tumor, we examined whether these could be combined to treat large established tumors." (PMID 37655661, 2023). "Additionally, tumor tissue has been found to contain CD4/CD8 double-positive T (DPT) cells, which may originate from infiltrating CD4+ or CD8+ single-positive (SPT) cells." (PMID 37576389, 2023). "The fact that FOXP3+ TILs, in contrast to CD8+ and CD4+ TILs, did not decrease in inner tumor areas further suggests that regulatory T-cells may better survive in the microenvironment of the tumor body." (PMID 36586079, 2023). "As a consequence, upregulation of IDO1 expression in tumor cells, programmed cell death 1 (PD-1) in CD8+ T cells and forkhead box P3 (FOXP3) in CD4+ T cells occur, overall impairing CD8+ T cells proliferation and promoting the conversion of CD4+ T cells to Tregs." (PMID 37122718, 2023). "The frequency of anti-tumor CD4 TRB clonotypes was 12.7-fold higher in host peritoneum than host spleen and 7.9-fold higher for CD8 TRB clonotypes, confirming our previous work, that anti-tumor memory CD4 and CD8 T-cells migrate to and expand at the site of challenge in tumor-cured mice." (PMID 37033929, 2023).
tumor (continued). "Additionally, there is a need to investigate mutual interdependence of CD4 and CD8 T cells in SARS-CoV-2 control in lungs, as shown in models of tumor immunity, where APCs in the tumor environment are required to coactivate CD4 and CD8 T cells to reduce tumor burden." (PMID 37796612, 2023). "Notably, transfer of 3 × 106 activated CD4+ T cells expressing the high avidity TCR 1 at 1 d before tumor challenge with SCC VII and green fluorescent protein (GFP) or luciferase (Luc) was sufficient to induce tumor rejection." (PMID 37400675, 2023). "Thus, it is reasonable to speculate that CD4+ T cells may play a role in the early stage of PDAC development, subsequently recruiting effector CD8+ T cells and macrophages to the tumor site to maintain the balance of the TME." (PMID 37405518, 2023). "R848@M2pep-MPsAFP significantly increased the numbers of CD4+ T cells, activated CD4+CD69+ T cells, CD8+ T cells, proliferated CD8+ T cells and activated CD8+CD69+ T cells, CD8+IFNγ+ T cells and CD8+GzmB+ T cells in tumor tissues compared with free R848, R848@MPs, R848@M2pep-MPs and R848@MPsAFP." (PMID 37704614, 2023). "An analysis based on the Tumor Immune Estimation Resource (TIMER; cistrome.shinyapps.io/timer) further confirmed the relationship between seven key CRGs and the abundance of six immune cells (B cells, CD8+ T cells, CD4+ T cells, macrophages, neutrophils and dendritic cells)." (PMID 37384293, 2023). "Some differences between CD4+ and CD8+ TCRs were intrinsic to T cell subsets as can also be observed in peripheral T cells from healthy individuals, while other were only found in TILs samples and therefore may be tumor-driven." (PMID 37600765, 2023). "Interestingly, the results of antibody blockade assays in the combination treatment group were different, where blocking either CD8+ T or CD4+ T cells resulted in the partial inhibition of tumor growth, indicating the CD8+ and CD4+ subsets each played important roles in anti-tumor effects." (PMID 37771774, 2023). "In this regard, various authors reported an independent prognostic effect for CD3, CD4 or CD8 T cells in HPV-positive OPSCC patients demonstrating a significant role of anti-tumor immune responses not only for anti-PD1 therapies but for OPSCC tumor control and response to RCTx in general." (PMID 37187729, 2023). "Immunohistochemically neoplastic cells are typically CD3+, CD7+, CD103+, TCRβ+/− cells, CD4−, CD8−, and CD5−, mostly expressing CD30 with CD56 negativity, and demonstrate an activated cytotoxic phenotype (perforin+, granzyme B+, and TIA-1+), reflecting the origin of the tumor from cytotoxic IELs." (PMID 37627888, 2023). "Remarkably, CD4+ T cell target antigen did not need to be tumor-restricted in both prophylactic and therapeutic settings and could instead be targeted to a universal MHC II-binding helper epitope." (PMID 37655661, 2023). "In this we were motivated by early results showing the human tumor cell lines expressing MHC-II molecules after transfection with CIITA could process and present peptides from M. Tuberculosis Ag85 protein to antigen-specific CD4+ T cell clones." (PMID 37467968, 2023). "Indeed, tumor microenvironmental signals, such as tumor antigens, cytokines (e.g., TGF-β) and metabolic factors (e.g., lactate and lipid metabolites), can drive naïve CD4+ T cell differentiation into Tregs, which are immunosuppressive phenotypes." (PMID 36765614, 2023). "Tumor infiltrate was very significant in GL261-CIITA tumors as compared to GL261 parental tumors and was mostly represented by CD3+ T lymphocytes, both CD4+ and CD8+ T cells (CD4+: 1,415 cells/mm2, CD8+: 989 cells/mm2 in GL261-CIITA; CD4+: 138 cells/mm2, CD8+: 72 cells/mm2 in GL261)." (PMID 36993983, 2023). "Interestingly, the role of helper CD4+ T cells in the tumour microenvironment is not as clear and obvious." (PMID 36980527, 2023).
tumor (continued). "TSLP has multiple functions in both homeostasis and pathological conditions, and this cytokine can act on B cells, DCs, CD4+ and CD8+ T cells, neutrophils, mast cells, basophils, eosinophils, type 2 innate lymphoid cells, natural killer T cells, smooth muscle cells and even tumour cells." (PMID 37165746, 2023). "In contrast, Th1‐like CD4+ T cells, characterized by the expression of CCL4, GZMA and GZMB were found to be involved in viral protein interactions, natural killer cell‐mediated cytotoxicity and the T cell receptor signaling pathway, revealing their positive roles in tumor immune defense." (PMID 36725337, 2023). "Indeed, except in rare cases, CD4+ T-cells are not cytotoxic and cannot kill tumor cells due to the lack of expression of HLA class II molecules by tumor cells." (PMID 36726965, 2023). "However, a study published last year reveals the convection-enhanced delivery of the oncolytic adenovirus Delta24-RGD to 20 patients with recurrent GBM provides a safe treatment in this phase 1 trial, with increased numbers of macrophages and CD4+ and CD8+ T cells found in the tumor specimens." (PMID 37445721, 2023). "Besides, they identified a cluster of cytotoxic GZMB CD4+ T cells that expressed high levels of PDCD1 and CTLA4, suggesting that this population could be involved in the anti-tumor response after immunotherapy." (PMID 36414693, 2023). "Within the tumor core and inner margin, more TCF1+ CD4 T cells and stem-like CD8 cells spatially localized with APC in primary tumors and lung metastases compared with liver and peritoneal metastases, but these were largely comparable in the outer invasive margin and juxta tumor regions." (PMID 37768208, 2023). "According to the Tumor Immune Estimation Resource (TIMER) database, ZNF385A and ZNF346 were significantly positively correlated with six main infiltrating immune cells in HCC, such as B cells, CD8 T cells, CD4 T cells, macrophages, dendritic cells, and neutrophils." (PMID 36834567, 2023). "Combination therapy elicited dramatic changes in both the myeloid and lymphoid compartments of the tumor microenvironment, including decreased infiltration of neutrophils and Arg1+ macrophages and increased infiltration of eosinophils, NK cells, CD8+ T cells, and CD4+ T cells." (PMID 37874652, 2023). "Notably, pretreatment of WT DCs with 2-DG reduced the numbers of tumor-infiltrating cGAMP-stimulated DCs, CD4+ T cells, and CD8+ T cells and decreased the frequencies of tumor-infiltrating IFN-γ–producing and granzyme B–producing CD4+ and CD8+ T cells." (PMID 36821379, 2023). "Furthermore, the proportion of proliferating tumor-infiltrated CD8+ T cells (Ki67+), but not CD4+ T cells, was significantly increased in tumor after administration of either OX40 antibodies." (PMID 37576888, 2023). "The activation of the adaptive immune system is also insignificant in the non-responders and thus, the non-responder concentrations of the effector CD8 + and CD4 + T cells, memory, and plasma B cells are near zero, which results in a low amount of tumor antigen and tumor cells with antibodies." (PMID 38076985, 2023). "E6-specific CD4+ T cells do not recognize or kill autologous tumor cells expressing MHC-II." (PMID 36512410, 2023). "By using single-cell RNA-sequencing (RNA-seq) technology, it has become clear that several CD4+ T helper cell subtypes infiltrate into the tumor microenvironment (TME); these are cytolytic CD4+ T cells that express high levels of granzymes and perforin and may contribute to the anti-cancer response." (PMID 38140230, 2023). "Hypofractionated RT of 8 Gy × 3f showed the best effect of primary tumor control with the significantly increased infiltration of CD8+ tumor‐infiltrating lymphocytes (TILs) and CD4+ TILs, whereas anti‐PD‐1 alone did not have any effect on either tumor control or immune cell infiltration." (PMID 37206639, 2023).
tumor (continued). "While the major role of CD4+ T cells, so-called T helper cells, is to support and regulate the responses of other immune cells, CD8+ T cells, so-called cytotoxic T cells, act on their own to directly clear a potential danger by eliminating, for example, virus-infected or tumor cells." (PMID 37893076, 2023). "Therefore, we conclude that GD-NT-induced anti-tumor immunity mainly relies on CD8+ T cytotoxic cells but not CD4+ T helper cells." (PMID 37495617, 2023). "Furthermore, the percentages of CD8 (+) T cells rather than CD4 (+) T cells were also remarkably increased from spleens tissues in mice bearing A20-silent tumor." (PMID 37607946, 2023). "The biomarker analysis showed that PD-L1 combined positive score (CPS), tumor CD68 and CD4 protein levels (representing cell surface protein markers for TAMs), and tumor-infiltrating CD4 T cells could be potential predictive markers for cabozantinib plus durvalumab activity in this setting." (PMID 37958363, 2023). "In this study, we isolated and identified the HLA-DPB1*03:01-restricted human TILs from patient’s tumor tissue that recognize natural processed and presented epitopes in KRASG12V mutants, and cloned the TCRs to construct KRASG12V-reactive TCR-engineered CD4+ T cells." (PMID 37287989, 2023). "Indeed, preclinical studies have demonstrated that in the absence of MHC-II on tumor cells, adoptively transferred Trp1 CD4+ T cells still can exert antitumor immunity dependent on IFN-γ and correlate with increased cytotoxic activity of macrophages." (PMID 36512410, 2023). "The addition of PD-1 blockade to NAC promoted anti-tumor immunity through T and B cells recruitment in the tumor microenvironment and induced tumor-infiltrating CD8+ T cells skewed toward CD127+ and KLRG1+ phenotypes, which may be assisted by CD4+ T cells and B cells." (PMID 37231145, 2023). "Moreover, under the 980 nm near‐infrared irradiation, the strongest type 1 T helper (Th1) and type 2 T helper (Th2) immune responses and the highest frequency of CD4+, CD8+, and effector memory T cells were observed in the colon cancer (CT26)‐tumor‐bearing BALB/c mice." (PMID 36479842, 2023). "Specifically, within the CD4+ T cell subpopulation, METTLE3 was found to be negatively correlated with Th2 and Th17 cells, which regulate inflammatory responses, while it was positively correlated with Th1 and Tfh cells, known for their crucial role in tumor immunotherapy." (PMID 38187373, 2023). "The antitumor response requires the activation of both CD4+ T cells, which are crucial for orchestrating and sustaining the initial response and generating immunological memory, and CD8+ T cells, which are crucial for their capacity to directly recognize and kill tumor cells." (PMID 37600765, 2023). "Interestingly, after 24 hours, ML-NK cells extravasated and migrated towards the tumor spheroid even in the absence of T cells, although the presence of CD4+ T cells increased the number of extravasating ML-NK cells." (PMID 37865647, 2023). "The frequencies of immune cells (CD4+ T cells, CD8+ T cell, Treg cells, NK cells and CTLs) and the concentrations of cytokines (including IL-6, IL-12, Interferon (IFN)-γ, IL-10 and TGF-β) in tumour tissues were used to evaluate the immune status of the tumour microenvironment." (PMID 37076492, 2023). "However, in EOC patients, metformin combined with platinum-based chemotherapy drugs does not enhance CD4+ cytotoxic T cells in the stroma of the tumor." (PMID 37686159, 2023). "Compared to non-responders, responders also had more CD3+ and CD4+ tumor-infiltrating lymphocytes." (PMID 37446056, 2023). "The t-SNE plotting of transcriptional data indicated that tumor-infiltrating T cells in rejecting Raji tumor were predominantly CD8+ T cells expressing activation and effector molecules such as granzyme A (GZMA) whereas matching splenic T cells were predominantly naive CD4+ T cells." (PMID 37087494, 2023).
tumor (continued). "Interestingly, no significant changes in CD3, CD4, NK, or B cells were found in the tumor draining lymph nodes across treatment groups." (PMID 37824211, 2023). "In addition, in the context of tumor immunity, a couple recent studies have also shown cDC1s to have an essential dual role in enhancing both CD8+ and CD4+ T cell activation and suggested the cDC1 activation of CD8+ T cells can not be separated from the dual role in activating CD4+ T cells." (PMID 37942313, 2023). "However, the results also demonstrated that even in the complete absence of CD4+ T cells, ML-NK cells were able to extravasate, although at a slower pace, and killed 35% of the tumor mass." (PMID 37865647, 2023). "There was an increase in number of CD4+ and CD8+ TEF cells and an increase in the fraction activated CD44+CD8+ T cells in dLN, a systemic increase of CD4+ and CD8+ TEF and TCM-like cells and enhanced T cell activation in the spleen of Shp2f/fLysMCre compared to Shp2f/f MC17-51 tumor-bearing mice." (PMID 36581713, 2023). "In addition, CXXC5 expression was positively correlated with infiltration of CD8+ T cells, resting memory CD4+ T cells, resting NK cells, activated dendritic cells, and memory B cells, suggesting that CXXC5 may be involved in CML anti-tumor immunity." (PMID 38283355, 2023). "Moreover, the flow‐like cytometry plots show that S100A5 was positively expressed mainly in CK19+ tumor cells (58.84%), but almost not in CD4+ T cells (2.45%) or CD8+ T cells (4.15%)." (PMID 37414584, 2023). "Based on our current findings, strategies that could capitalize on the infiltration of double-negative T-cells or conversely enhance CD4+/CD8+ recruitment to the tumor may be beneficial, as may be strategies to dampen the PD-1/PD-L1 axis." (PMID 38169670, 2023). "These cells do not express adjuvant (CD4+) or cytotoxic (CD8+) activity against tumor cells." (PMID 36872320, 2023). "The expression levels of ANXA1 were negatively correlated with tumor purity (r=-0.271, P=1.64e-05), but positively correlated with the levels of infiltrating B cells (r=0.04, P=5.4e-01), CD8+ T cells (r=0.175, P=6.64e-03), CD4+ T cells (r=0.256, P=6.15e-05), macrophages (r=0." (PMID 36988561, 2023). "Furthermore, tumour draining lymph nodes exhibited a significant (p < 0.05, p < 0.005, and p < 0.005, respectively) increase in the number of F4/80+CD11b+ cells (macrophages), CD8+ cells (CTLs), and CD4+ cells (T helper cells) 2 days after treatment." (PMID 37631324, 2023). "At present, in addition to conventional antitumor therapy and recently emerging ICIs, tumor immunotherapy is being developed from different aspects, such as innate immunity (natural killer T (NKT) and natural killer (NK) cell activation) and adaptive immunity (CD4+ and CD8+ T cell activation)." (PMID 36830717, 2023). "The tumor tissue alaysis demonstrated the greatest differences relative to two other tissues in the liposomal combination therapy group (Lip-EPA + Lip-gp100) in the number of the CD4 + T cells over monotherapy and non-liposomal EPA + gp100 groups." (PMID 37037839, 2023). "Conversely, CD4+ T, with high expression of PD-1, were considered exhausted and were found to be a negative prognostic indicator for ICI therapy 53; thus, the biological activities that contribute to the activation of anti-tumor CD4+ T merit further investigation." (PMID 37771774, 2023). "A. muciniphila can produce inosine, induce the expression of TH1 regulatory genes in CD4+ T cells, and reverse PD-1 blockade by IL-12 from dendritic cells, increasing the recruitment of CCR9+ CXCR3+ CD4+ T lymphocytes to the tumor microenvironment to kill tumor cells." (PMID 37416062, 2023). "Decreased infiltration of the tumor by CD4+ and CD8+ T cells and the increased presence of regulatory T cells as well as TH2 cytokines (IL [interleukin]-4, IL-5), transforming growth factor (TGF)-β, and IL-10, also lead to an immunosuppressive environment in the tumor." (PMID 36230474, 2022).